PTPN2 (protein tyrosine phosphatase non-receptor type 2)
Diseases named in the same sentence as PTPN2 in open-access papers (continued):
Sharing a sentence is not in itself a finding about the gene and the disease.
tumor (continued). "The gene copy number status of PTPN2 could be analysed in 146 available tumour samples, whereas PTPN2 protein expression could be assessed in 664 tumours." (PMID 30515568, 2019). "Dividing tumours by their Nottingham grade (NHG), a trend was found where low PTPN2 expression indicated a higher risk for distant recurrence in NHG 1 tumours (HR = 0.41, 95% CI0.12–1.42, P = 0.16) compared with NHG 2–3 tumours (HR = 1.34, 95% CI 0.83–2.15, P = 0.23)." (PMID 30515568, 2019). "The proposed PTPN2 substrate Met was found to be associated with PTPN2, membranous and cytoplasmic phosphorylated Met were more often positive in PTPN2-positive tumours, which was specifically apparent in the Luminal A subtype (cytoplasmic pMet: p < 0.005 and membranous pMet: p = 0.038)." (PMID 31025094, 2019). "We found that PTPN2 transcript levels increased with the tumor grade." (PMID 29764444, 2018). "In addition, we compared mRNA expression levels of PTPN2 in 109 paired target tissue samples from The Cancer Genome Atlas (TCGA) and found that PTPN2 mRNA expression levels were significantly increased in tumor tissues than normal tissues (P = 3.01E-05)." (PMID 28400551, 2017). "Moreover, eliminating PTPN2 in tumor cells primes antitumor immunity by sensitizing tumors to IFNγ." (PMID 39065585, 2024). "Thus, targeting PTPN2 by CRISPR technology could be an effective method to enhance caner immunity effects to inhibit tumor recurrence and metastasis." (PMID 38898493, 2024). "Therefore, the extent to which the inhibition of PTP1B and/or PTPN2 in DCs with Compound 182 might ultimately impact on tumor growth remains unclear." (PMID 37500611, 2023). "However, consistent with published reports, we showed that PTPN2/N1 inhibition enhances T cell activation, which could also increase anti-tumour immunity." (PMID 37794185, 2023). "Furthermore, it is important to recognize that in some circumstances, the inhibition of PTP1B and/or PTPN2 in tumor cells might instead contribute to tumor growth." (PMID 37500611, 2023). "As loss of either PTPN2 or PTPN1 increased the sensitivity of tumour cells to checkpoint blockade in an in vivo CRISPR screen, and because both phosphatases dampen immune cell activation, we sought to identify a dual PTPN2/N1 inhibitor to further enhance anti-tumour activity." (PMID 37794185, 2023). "Moreover, the complex cellular and stromal environment is crucial for tumor development, and whether PTPN2 regulates cellular and stromal changes within the TME is one direction for future research." (PMID 36077422, 2022). "Tumor immune microenvironment analysis further revealed that downregulation of the Ptpn2 gene could enhance the activation of CD8+ T cells, polarization of M1 macrophages, and induction of DC maturation while promoting the release of cytokines, thus, eliciting an immunotherapeutic effect." (PMID 35233535, 2022). "Numerous studies have shown that the knockdown of the PTPN2 gene in mouse T cells not only promotes T-cell expansion and conversion of progenitor T cells to cytotoxic T cells but also promotes the release of granzyme B from cytotoxic T cells, enhancing the ability to kill tumor cells." (PMID 36012144, 2022). "Therefore, targeting PTPN2 may provide a means for enhancing the anti‐tumour activity of T cells and extending the utility of CAR T cells beyond haematological malignancies to solid cancers." (PMID 31803974, 2020). "Therefore, PTPN2‐deficient CAR T cells eradicate tumours without promoting systemic inflammation and immunopathologies." (PMID 31803974, 2020). "Although it may be possible to target PTPN2 systemically with drugs to enhance T‐cell and CAR T‐cell responses and potentially achieve synergistic effects through the targeting of PTPN2 in both tumour cells and T cells/CAR T cells, there are several important considerations." (PMID 31803974, 2020).
tumor (continued). "We found that 55% of mice receiving PTPN2‐deficient OT‐1 naive CD8+ T cells were tumour‐free at 55 days post‐adoptive transfer, whereas only 18% of mice receiving control OT‐1 naive CD8+ T cells were tumour‐free and this was accompanied by the increased presence of OT‐1 CD8+ TRMs in the skin." (PMID 31803974, 2020). "Consistent with our previous studies, PTPN2‐deficient CD25hiFoxP3+ regulatory T cells (Tregs) were increased rather than decreased in AT‐3‐OVA tumours and their activation was moderately enhanced precluding the repression of tumour growth being due to defective Treg‐mediated immunosuppression." (PMID 31803974, 2020). "Moreover, PTPN2‐deficient CAR T cells were effective in repressing tumour growth even without the co‐administration of IL‐2 that is used routinely in rodent pre‐clinical models to promote CAR T‐cell expansion but is not used in the clinic." (PMID 31803974, 2020). "For instance, PTPN2, a phosphatase that dampens IFN-γ signaling through dephosphorylation of STAT1 and JAK1, negatively regulates tumor antigen presentation and impedes cytokine-driven tumor inhibition 73-75." (PMID 41281758, 2025). "Oral PTPN2 inhibitor ABBV‐CLS‐484 disrupts mitochondrial renewal and blocks TFRC‐mediated mitophagy to exert anti‐tumor activities, supporting clinical development for ALK+ ALCL." (PMID 40734623, 2025). "Eliminating PTPN2 potentiates IFN-γ signaling, augments antigen presentation, and intensifies cytokine-driven tumor growth inhibition, suggesting potential therapeutic benefits from its inhibition." (PMID 41281758, 2025). "We have demonstrated that PTPN2 promotes mitochondrial renewal through PINK1‐PRKN‐dependent mitophagy by suppressing TFRC expression, thereby exerting tumor‐promoting effects in ALK+ ALCL." (PMID 40734623, 2025). "In the context of tumor immunity, PTPN family members (PTPN6, PTPN3, PTPN2, PTPN1) shape the tumor microenvironment by regulating the development and function of immune cells, thereby influencing tumor progression and the efficacy of immunotherapy." (PMID 40570022, 2025). "Taken together, these results implied the successful reprograming of tumor microenvironment with DOX/ISL treatment and PTPN2 targeted immunotherapy." (PMID 38898493, 2024). "The M(I + D)PH group induced the highest level of intratumoral infiltration of CD3+CD8+ T cells in tumor-bearing mice, which indicated the amplified anti-tumor immunity by DOX/ISL treatment and PTPN2 targeting." (PMID 38898493, 2024). "Nonetheless, our preclinical studies point toward the existence of a therapeutic window for safely and effectively targeting PTPN2 and/or PTP1B and enhancing anti-tumor immunity and the response to immunotherapy." (PMID 37500611, 2023). "We collected 87 signatures related to TME and tumor phenotypes from the IOBR package and analyzed the correlation between PTPN2 expression and these signatures." (PMID 37884566, 2023). "We found that the deletion of PTPN2 in T cells resulted in robust p-STAT-1 within the nuclei of AT3-OVA tumor cells; both the number of p-STAT-1 positive tumor cells and p-STAT-1 intensity were increased by the deletion of PTPN2 in T cells." (PMID 37500611, 2023). "Although we cannot exclude contributions from B cells, these results are consistent with the repression of tumor growth being attributed to the inhibition of PTP1B and/or PTPN2 in T cells." (PMID 37500611, 2023). "The protein tyrosine phosphatases PTPN2 and PTPN1 are central regulators of inflammation, and their genetic deletion in either tumour cells or immune cells promotes anti-tumour immunity." (PMID 37794185, 2023). "Genetic deletion of PTPN2 or PTPN1 in T cells can increase T cell proliferation and cytokine production in vitro and prevent tumour outgrowth in vivo." (PMID 37794185, 2023).
tumor (continued). "Our studies indicate that the deletion of PTPN2 in T cells or the administration of Compound 182 similarly recruits TILs and promotes T cell activation in immunogenic AT3-OVA tumors to repress tumor growth." (PMID 37500611, 2023). "PTPNs/PTPN2 can not only affect the growth of the PAAD, but also promote PAAD cells infiltration, affect the expression of immune checkpoints, and increase tumor response to immunotherapy." (PMID 35154122, 2022). "Therefore, the reduced ability of PTPN2-deficient/kncokdown macrophages to develop into alternatively activated (M2) macrophages during inflammation might contribute to the enhanced inflammation but reduced tumor load that we previously observed in PTPN2-LysMCre mice." (PMID 34420044, 2022). "M1HD@RPR can directly kill tumor cells and stimulate immunogenic cell death (ICD) by DOX and downregulate Ptpn2." (PMID 35233535, 2022). "Knockdown of PTPN2 results in enhanced ICB therapeutic efficacy by promoting antigen presentation and IFN–γ signaling in tumor cells." (PMID 34532286, 2021). "In particular, our studies demonstrate that the deletion of PTPN2 not only drives the homing of CAR T cells to solid tumours, but also their activation to eradicate tumours in an otherwise immunosuppressive tumour microenvironment." (PMID 31803974, 2020). "While in the present study no direct association was found between PTPN2 and subtypes, PTPN2 low protein expression was correlated with a negative ER status, which is per definition non-Luminal and related to more aggressive disease compared with ER-positive tumours." (PMID 31025094, 2019). "Patients with tumours harbouring both low PTPN2 expression and low membranous pMet expression had a worse DRFS compared with patients with high PTPN2 expression and low pMet." (PMID 31025094, 2019). "Both RPTP-κ and PTPN2 knockdown increase levels of p-EGFR/Y1173 and of p-ERKs, indicating a tumor suppressor activity of these PTPs and/or a mitogenic function of EGFR/Y1173 phosphorylation." (PMID 26079946, 2015). "In contrast to ALK+ ALCL, PTPN2 knockout did not significantly impair cell proliferation, induce apoptosis, or exhibit tumor‐promoting effects in FARAGE, RAJI, and JURKAT." (PMID 40734623, 2025). "Specifically, they suppress CD8+ T cell immune responses by downregulating protein tyrosine phosphatase non-receptor type 2 (PTPN2) expression, which accelerates tumor progression." (PMID 40486875, 2025). "In addition, SOCS1 and PTPN2 were inhibited in REGNASE-1-null CD8+ T cells, resulting in robust proliferation of effective CD8+ T cells in tumours." (PMID 38581063, 2024). "The deletion of PTPN2 in the hematopoietic compartment repressed tumor growth and increased TILs, but this was not more pronounced than that associated with the deletion of PTP1B or PTPN2 in T cells." (PMID 37500611, 2023). "Thus, PTPN2/N1 inhibition leads to a greater infiltration of total immune cells and CD8+ cells into tumours." (PMID 37794185, 2023). "The repression of tumor growth and the recruitment of T cells, including cytotoxic CD8+ T cells, was generally more pronounced when PTPN2 was deleted in T cells, whereas the repression of tumor growth by Compound 182 more closely resembled the effects of deleting PTP1B in T cells." (PMID 37500611, 2023). "Thus, treatment of tumour cells with AC484 phenocopies the effects of deletion of both Ptpn2 and Ptpn1 on cell growth and ISG expression in response to IFN, and enhances tumour sensitivity to T cell-mediated toxicity." (PMID 37794185, 2023). "IFN-γ signalling was inhibited by protein tyrosine phosphatase non-receptor type 2 (PTPN2) whose deletion in tumour cells increased ICBT efficacy by enhancing IFN-γ-mediated effects on antigen presentation and cell growth inhibition." (PMID 37503572, 2023).
tumor (continued). "As with the deletion of PTPN2 in T cells, we found that the systemic administration of Compound 182 and the repression of AT3-OVA tumor growth also increased p-STAT-1 staining within the tumor, as well as the abundance of CD3ε+ T cells." (PMID 37500611, 2023). "In this study, we sought to determine whether small-molecule inhibitors of Ptpn2 could replicate the phenotype previously reported for Ptpn2-null B16F10 cells and sensitize this resistant tumor to ICIs." (PMID 36968224, 2023). "We found that the deletion of either PTP1B or PTPN2 in NK cells had no significant impact on tumor growth and mouse survival." (PMID 37500611, 2023). "But in some studies, the absence of PTPN2 in B16 tumours does not produce significant differences in bone marrow cell infiltration." (PMID 37884566, 2023). "Here we showed that PTPN2/N1 inhibition reduces exhaustion and increases T cell memory signatures, as we observed reduced expression of PD-1, TOX and TIM-3 in chronically antigen-stimulated or tumour-infiltrating CD8+ T cells." (PMID 37794185, 2023). "Since PTPN2 promotes FoxP3/Treg stability, the KDDN results suggest that JGT may inhibit immunosuppressive Foxp3 cells in the tumor microenvironment." (PMID 36980301, 2023). "Lack of PTPN2 in tumor cells enhances immunotherapy efficacy through augmenting interferon-mediated antigen presentation and growth inhibition." (PMID 35957898, 2022). "The signaling of GSK-3, PTPN2, SHP2, and CDK4/6 all decrease PD-L1 expression on tumor cells." (PMID 35911672, 2022). "As mentioned, both mammalian orthologues of PTP61F, PTP1B and TCPTP (encoded by PTPN1 and PTPN2, respectively), have roles in multiple cancers, though not necessarily as tumor suppressors." (PMID 34884538, 2021). "Both KRAS and PTPN2 knockdown could dramatically decrease the phosphorylation levels of MEK and ERK in KRAS-dependent tumor cell lines HCT-116, PaTu8988T, and H460." (PMID 33122197, 2020). "The effect of PTPN2 knockdown is no less than that of KRAS knockdown in KRAS-dependent tumor cell lines, suggesting that PTPN2 is required for the cell survival signaling of KRAS." (PMID 33122197, 2020). "Patients with tumours expressing low levels of PTPN2 had no significant benefit from tamoxifen treatment (P = 0.14), whereas the group with high protein expression did have benefit (P = 0.00005, interaction test P = 0.11)." (PMID 30515568, 2019). "This has earlier been shown in a previous study where protein loss was associated with worse survival in NHG 1 tumours, indicating that PTPN2 is not prognostic in high-grade tumours, merely in low-grade tumours." (PMID 31025094, 2019). "Ptpn2‐deficient CD8+ T cells show an increase in the generation, proliferative potential, and cytotoxic activity of Tim‐3+ cells without alteration of Tpex cells, leading to better tumour control." (PMID 39169517, 2024). "We have shown previously that the deletion of PTP1B or PTPN2 in T cells can enhance T cell activation and cytotoxicity in vitro by promoting TCR and/or cytokine signaling, whereas in vivo the deletion of PTPN2 or PTP1B in T cells can markedly enhance anti-tumor immunity." (PMID 37500611, 2023). "Although in the longer term, tumor-intrinsic resistance to PTP1B/PTPN2 inhibition may eventuate, the beneficial anti-tumor effects of PTP1B/PTPN2 inhibition in T cells would nonetheless persist." (PMID 37500611, 2023). "Given that Ptpn2 sgRNA depletion is only seen in the in vitro screen condition in which anti-mCD19 CAR-T cells were added, these data suggest that mCD19-mediated release of IFNγ from anti-mCD19 CAR-T cells can exert anti-tumor activity in our in vitro screen conditions." (PMID 38052854, 2023). "As PTPN2/N1 inhibition lowered the threshold for TCR signalling and T cell activation, in addition to enhancing the presentation of tumour antigens, AC484 may affect the repertoire of tumour-reactive T cells." (PMID 37794185, 2023).
tumor (continued). "To specifically determine the extent to which the induction of anti-tumor activity by Compound 182 may be reliant on targeting PTP1B and/or PTPN2 in T cells, we next asked if Compound 182 could repress the growth of AT3-OVA tumors in Rag1–/– (C57BL/6) mice that lack T cells and B cells." (PMID 37500611, 2023). "PTPN2 deletion in CD8+ T cells also boosts the generation, proliferation, and cytotoxicity of Tim-3+ terminally exhausted subpopulation without altering the Slamf6+ progenitor exhausted subpopulation, which enhances anti-tumor responses and improves tumor control." (PMID 36077422, 2022). "Many researches have revealed that the absence of PTPN2 can potentiate anti-tumor immune effects." (PMID 35154122, 2022). "PTPN2 deletion increases IFN-γ-induced STAT1 phosphorylation, expression of antigen processing and/or presentation related molecules (Tap1, Tapbp, B2m, MHC-I, and MHC-II), as well as expression of some chemokines (Cxcl9, Cxcl10, Cxcl11, and Ccl5), which recruit T cell infiltration into the tumor." (PMID 36077422, 2022). "Similarly, the decreased expression of the tumor suppressor and apoptosis-inducing factor PDCD4 might play a role in the increased survival of PTPN2 KO T cells." (PMID 32726622, 2020). "However, negative selection as monitored by the deletion of Vβ5+ and Vβ3+ TCR SPs by the endogenous MMTV (mouse mammary tumour provirus) 6 and 8 superantigens in 14–16 day-old Ptpn2−/− (BALB/c) mice was not diminished, but rather modestly enhanced." (PMID 22590589, 2012). "Indeed, in T cell-specific PTPN2-deficient mice, Compound 182 had no significant additional effect on STAT-1 signaling and TILs and only moderately enhanced T cell cytotoxicity and the repression of AT3-OVA tumor growth." (PMID 37500611, 2023). "Furthermore, deletion of PTPN1 and PTPN2 in DCs stimulated the growth of IL-12 and IFN-γ, which amplified the IL-12/STAT4/IFN-γ/STAT1/IL-12 positive autocrine loop, boosting the therapeutic potential of mature monocyte-derived dendritic cells (moDCs) in tumor-bearing mice." (PMID 35957898, 2022). "Therefore, targeting PTPN2 may not only enhance the antigen‐specific activation and function of CAR T cells, but also limit “on‐target off‐tumour” toxicities by driving the homing of CXCR3‐expressing CAR T cells to CXCL9/10/11‐expressing tumours." (PMID 31803974, 2020). "Thus, inhibition of PTPN2 could suppress KRAS cancer, whereas enhancing tumor immunity." (PMID 33122197, 2020). "Although PTPN2‐deficient CAR T cells increased core temperature as early as 5 days post‐adoptive transfer (Fig EV4B), this is to be expected for a developing immune response and this did not persist after tumours were cleared and did not affect body weight (Fig EV4B and C)." (PMID 31803974, 2020). "In mice treated with Ptpn2-/- CAR-T cells, tumor control is achieved without autoimmunity and severe morbidity for up to 70 days post-transfer." (PMID 38022587, 2023). "Synergistic tumor inhibitory effects were achieved by the treatment of isoliquiritigenin (ISL) with doxorubicin (DOX), which were enhanced by CRISPR-based gene editing to target protein tyrosine phosphatase non-receptor type 2 (PTPN2) to initiate long-term immunotherapy." (PMID 38898493, 2024). "Given that PTPN2 is a negative feedback regulator of IFNγR/JAK/STAT signaling, we hypothesized that depletion of anti-Ptpn2 sgRNA expressing cells in vitro may result from hypersensitization of tumor cells to IFNγR signaling." (PMID 38052854, 2023).